TMEM217 (transmembrane protein 217)
Synonyms: C6orf128; dJ355M6.2
Tractability: Antibody: UniProt predicts a signal peptide or a membrane-spanning region.
Gene: Protein-coding gene on chromosome 6 (37,212,180 to 37,258,155, reverse strand). Ensembl gene ENSG00000172738.
Subcellular location: Membrane
Subcellular location (Human Protein Atlas): Nucleoli; Cytosol
Gene Ontology:
Biological process: flagellated sperm motility
Cellular component: sperm flagellum; sperm plasma membrane; membrane
Genetic constraint (gnomAD): Loss-of-function variants: 1 observed, 1.95 expected, observed/expected ratio (o/e) 0.51, 90% interval 0.17 to 1.75. That is too few expected variants to judge how well the gene tolerates losing a copy. Missense variants: 201 observed, 257.24 expected, observed/expected ratio (o/e) 0.78, 90% interval 0.7 to 0.88. Synonymous variants: 75 observed, 90.88 expected, observed/expected ratio (o/e) 0.83, 90% interval 0.68 to 1.
Homologues: Orthologues: chimpanzee TMEM217 (96% identical), macaque TMEM217 (81% identical), pig TMEM217 (57% identical), dog TMEM217 (56% identical), rabbit TMEM217 (55% identical), mouse Tmem217 (49% identical), rat Tmem217 (41% identical). Paralogues in human: TMEM217B (20% identical).
Diseases named in the same sentence as TMEM217 in open-access papers:
TMEM217 is named in the same sentence as 6 diseases in open-access papers, as found by Europe PMC text mining. Sharing a sentence is not in itself a finding about the gene and the disease. The quoted sentences say what the papers report.
acute myeloid leukemia (2 papers, 2021 to 2024). Acute myeloid leukemia (AML) is a group of neoplasms arising from precursor cells committed to the myeloid cell-line differentiation. "We note that TMEM217 is highly induced in leukemia samples assayed with GeneChips and RNA sequencing and patients diagnosed with acute myeloid leukemia (LAML) show a decreased survival rate when the gene is highly expressed." (PMID 33426787, 2021).
ciliopathies (1 paper, 2019). "TCTN1 is also a known protein component of a ciliopathy-associated protein complex and could interact with Mks1, Tmem216, Tmem217, and several other proteins that are associated with ciliopathies to modulate ciliary assembly and trafficking." (PMID 31297133, 2019).
Infertility (1 paper, 2025). "We confirmed that male fertility was restored in Tmem217 KO mice carrying a transgene encoding TMEM217, demonstrating that infertility was not due to off-target effects." (PMID 41091759, 2025). "In addition, we found that fertilizing ability can be restored in Tmem217 KO spermatozoa using specialized IVF media including cAMP analogs, which may provide a strategy for overcoming infertility associated with defects in cAMP-dependent pathways." (PMID 41091759, 2025).
male infertility (1 paper, 2025). The inability of the male to effect fertilization of an ovum after a specified period of unprotected intercourse. "Knockout (KO) of Tmem217 in mice resulted in sperm motility defects and male infertility, phenocopying Slc9c1 KO mice." (PMID 41091759, 2025). "To understand the cause of male infertility, we first analyzed testes, but no abnormalities were found in weights or sections of Tmem217 KO testes." (PMID 41091759, 2025).
cancer (1 paper, 2021). A tumor composed of atypical neoplastic, often pleomorphic cells that invade other tissues. "TMEM217's function and its expression in normal and cancer tissues are currently unknown." (PMID 33426787, 2021).
TMEM217 also shares sentences with these, for which no sentence is quoted: leukemia (1 paper).